IL13 (interleukin 13)
Diseases named in the same sentence as IL13 in open-access papers (continued):
Sharing a sentence is not in itself a finding about the gene and the disease.
ischemic stroke (17 papers, 2018 to 2025). A stroke disorder caused by obstruction of blood flow to the brain, due to thrombotic (local blood clot formation) or embolic (due to a blood clot or other material traveling from another site) event. "Among these, anti-inflammatory cytokines, particularly, interleukin-13 (IL-13) and Interleukin-4 (IL-4), delivered via the intranasal route, were reported to promote white matter recovery in ischemic stroke." (PMID 41304786, 2025). "Another study also demonstrated that IL-13 improved long-term recovery in mice after ischemic stroke." (PMID 39578419, 2024). "On the contrary, a recent study demonstrated that IL‐13 promoted the polarization of microglia toward the M2 phenotype by inhibiting STAT3 phosphorylation after ischemic stroke." (PMID 37869777, 2024). "To investigate the potential involvement of IL-13 in the beneficial effects of L-DOPA in ischemic stroke, we assessed its expression in ischemic brain tissue." (PMID 39578419, 2024). "Inhibition of p-STAT3 is involved in the microglia/macrophages polarization, white matter repair and long-term neuronal protection provided by IL-13 after ischemic stroke." (PMID 35578342, 2022). "Our recent study demonstrated that pro-inflammatory monocytes migrate shortly after an ischemic stroke and are converted by interleukin (IL)-4 and IL-13 into anti-inflammatory macrophages that attenuate ischemic stroke." (PMID 35634277, 2022). "The mechanism(s) by which IL-13-induced alterations in STAT3 signaling modifies ischemic stroke outcomes remains to be clarified." (PMID 35578342, 2022). "Mechanistically, IL-13 improved the long-term outcome after ischemic stroke by promoting the polarization of microglia/macrophages toward the anti-inflammatory phenotype at least partially by inhibiting the phosphorylation of STAT3." (PMID 35578342, 2022). "IL-13 promotes white matter repair and improves neurofunctional outcomes after ischemic stroke by modulating microglia/macrophages via inhibition of STAT3 phosphorylation." (PMID 35578342, 2022). "IL-13 treatment promoted a major increase of M2a phenotype, resembling microglia/macrophages following ischemic stroke in the ipsilateral hemisphere when compared to vehicle treatment (p = 0.0381)." (PMID 31372938, 2019). "Our study reports for the first time in the animal model of ischemic stroke the beneficial actions of i.v. administered anti-inflammatory cytokine IL-13." (PMID 31372938, 2019). "Our results showed that IL-13 treatment significantly decreased the time needed to remove the adhesive from the contralateral front paw in the late stage after ischemic stroke, at 14 dpi (p = 0.0345)." (PMID 31372938, 2019). "To further analyze the phenotype of recruited microglia and macrophages within the ischemic stroke lesion, as well as the effect of IL13-MSC thereon, we first performed additional immunofluorescence staining for Arg-1." (PMID 29866203, 2018). "We focused on addressing important applications of IL13-expressing MSCs as a new potential therapeutic approach for ischemic stroke." (PMID 29866203, 2018). "Our results have provided confirmatory evidence that transplantation of IL13-MSCs, which continuously secrete IL13, is able to polarize both microglia and macrophages to a neuroprotective M2 phenotype during the pro-inflammatory status in ischemic stroke." (PMID 29866203, 2018). "Studies have highlighted the neuroprotective effects of IL-13 in ischemic stroke." (PMID 39578419, 2024). "Previous studies have confirmed the indispensable role of IL-13 in ischemic stroke." (PMID 35173738, 2022). "Moreover, IL13 serves as an excellent candidate for more effective modulation of inflammatory responses in ischemic stroke, strongly decreasing the pro-inflammatory cytokine secretion, reducing inflammatory cell infiltration, and suppressing axonal loss." (PMID 36330425, 2022). "Accordingly, IL-13 is an attractive, novel therapeutic target in ischemic stroke." (PMID 35578342, 2022).
ischemic stroke (continued). "However, few studies have examined the effects of IL-13 on long-term outcomes after ischemic stroke." (PMID 35578342, 2022). "Further, the role IL-13 plays in microglia/macrophage-mediated immune responses, white matter injury, and long-term neurological outcomes after ischemic stroke remain unknown." (PMID 35578342, 2022). "However, IL-4 and IL-13 levels continued to be higher than those of the other cytokines on days 3 and 7 after ischemic stroke." (PMID 33409730, 2021). "Thus, our data show that IL-13 is neuroprotective and serves as a candidate for the treatment of ischemic stroke." (PMID 31372938, 2019). "Based on the previous data demonstrating IL-13’s beneficial, anti-inflammatory actions in some models of neurological disorders, testing the immunomodulatory potential of exogenous IL-13 administration was highly justified in the context of ischemic stroke." (PMID 31372938, 2019). "Our in vivo data suggested that IL-13-mediated neuroprotection in ischemic stroke might be exerted by alternatively polarized peripheral immune cells infiltrating the ischemic infarct site." (PMID 31372938, 2019). "In addition to this region-dependent distribution, we here demonstrate a strong effect on modulation of the polarization of resident microglia and infiltrated macrophages through the IL13 secretion by transplanted MSCs after ischemic stroke." (PMID 29866203, 2018). "Therefore, our results support the beneficial role of IL-13 in ischemic stroke." (PMID 39578419, 2024). "Whether IL-13 regulates STAT6 signaling in response to ischemic stroke remains to be determined." (PMID 35578342, 2022). "Thus, the protective effect of IL-13 in ischemic stroke could be partially explained by the reduced infiltration of peripheral immune cells and increased proportion of M2-skewed cells in the ipsilateral hemisphere." (PMID 31372938, 2019). "In summary, this study focused on the role of IL-13 as an endogenous regulator in L-DOPA-induced improvement of functional motor recovery and prevention of striatonigral degeneration in mice after an ischemic stroke." (PMID 39578419, 2024). "We further investigated the effect of L-DOPA on IL-13 and immune responses, providing detailed insight into the neuroprotective mechanism of L-DOPA in ischemic stroke." (PMID 39578419, 2024). "In this study, we focused on the role of IL-13, an anti-inflammatory cytokine, as a mechanism for the beneficial effect of L-DOPA in ischemic stroke." (PMID 39578419, 2024). "However, it is not clear whether IL-13 is beneficial after ischemic stroke long-term and the underlying molecular mechanism(s) remain unknown." (PMID 35578342, 2022). "The second aim of this study was to discover whether MSC-based delivery of IL13 can modulate the spontaneous polarization shift of anti-inflammatory (M2) to pro-inflammatory (M1) phenotypes in microglia and macrophages during the second week after ischemic stroke." (PMID 29866203, 2018). "In this study, we are the first to determine the immunomodulatory potential of MSC and IL13-expressing MSC engraftment in adjusting the polarization of brain-resident microglia and infiltrated macrophages in an ischemic stroke model." (PMID 29866203, 2018). "In the early stage of ischemic stroke, these immune cells can acquire a protective function known as anti-inflammatory (M2) phenotype, i.e., presenting characteristic features comparable to in vitro IL4 and/or IL13 polarized cells." (PMID 29866203, 2018). "However, it is not clear how dopaminergic signaling regulates IL-13 in the context of ischemic stroke." (PMID 39578419, 2024). "In conclusion, we reported a previously undefined molecular target of IL-13 in the CNS, namely that IL-13 played a neuroprotective role at least partially by inhibiting the activation of STAT3, which has been shown to mediate pro-inflammatory responses in microglia in response to ischemic stroke." (PMID 35578342, 2022).
prostate carcinoma (17 papers, 2011 to 2026). A carcinoma that arises from epithelial cells of the prostate gland. "We also investigated IL-13 rs1800925 polymorphisms on prostate-specific antigen levels as an indicator for risk of prostate cancer development." (PMID 34048465, 2021). "Furthermore, we investigated the implications of IL-13 rs1800925/-1112C/T variants on the risk of prostate cancer development in male individuals residing in Murehwa District, Zimbabwe." (PMID 34048465, 2021). "The connection between IL-13 and cancer cell migration and invasion has been increasingly explored, with IL-13 identified as a key player in several cancers, including prostate cancer." (PMID 40247153, 2025). "Studies have shown that type 2 innate lymphoid cells are enriched in prostate cancer, which produce interleukin (IL)-4 and IL-13, and are known to regulate tumor microenvironment and promote cancer proliferation." (PMID 38889686, 2024). "Increased syncytin-1 and annexin-V expression levels concomitant with an enhanced fusion frequency were observed in IL-4- and IL-13-treated PC3 prostate cancer cells." (PMID 35562905, 2022). "Co-cultivation of PC3 prostate cancer cells and primary human myoblasts yielded in higher IL-4 and IL-13 serum levels, which induced syncytin-1, annexin V, and CD133 expression in PC3 cancer cells that was further correlated with an enhanced fusion frequency." (PMID 35562905, 2022). "High levels of Th2 cytokines including IL-13 have been observed in the tumour microenvironment and peripheral blood of individuals with bladder, breast and prostate cancers." (PMID 34048465, 2021). "IL-13-expressing ILC2s are often associated with increased MDSC differentiation and pro-tumorigenic functions in bladder cancer, prostate cancer and acute promyelocytic leukemia." (PMID 33535624, 2021). "IL-13 is also important in prostate tumorigenesis, as receptors for IL-13 are expressed by several cancers including prostate carcinoma." (PMID 33005103, 2020). "The effects of the cytokines TNF-α, TRAIL, IFN-γ, IFN-α, IFN-β, IL-13, and IL-1β on cell death and/or cell viability have been investigated in various prostate carcinoma cell lines such as LNCaP, PC-3, DU-145, and M12." (PMID 24982891, 2014). "Here, we have undertaken a clinical investigation of the role of two closely related cytokines, IL-4 and IL-13 in prostate cancer." (PMID 24213139, 2011). "Treatment of recurrent prostate cancer patients with 200 μmol/day of SFN-rich broccoli sprout extract for 20 weeks also caused a statistically significant decrease in plasma levels of IL-1β, IL-4, and IL-13." (PMID 41802185, 2026). "Furthermore, a generalized linear mixed model identified statistically significant associations between prostate cancer risk and SNPs in IL12RB2, IL13, IL17A, IL4R, MAPT, and TFNRS1B." (PMID 37108754, 2023). "Moreover, IL13Rα2 protein was highly expressed in aggressive and metastatic prostate cancer cells and antagonized IL‐13 function." (PMID 36806727, 2023). "Lack of confirmed prostate cancer cases could have limited assessment of the association of IL-13 cytokine levels or IL-13 -1112C/T variants and risk of prostate cancer." (PMID 34048465, 2021). "Therefore, IL-13 levels and IL-13 rs10800925 may not be utilised as a biomarker for risk of prostate cancer in schistosome infections." (PMID 34048465, 2021). "Hence, the IL-13-1112C/T genotype may not be utilised as a biomarker for risk of prostate cancer." (PMID 34048465, 2021).
sarcoidosis (17 papers, 2012 to 2025). Sarcoidosis is a multisystemic disorder of unknown cause characterized by the formation of immune granulomas in involved organs. "In sarcoidosis, exosomes cause the initiation and progression of inflammatory responses by enhancing the induction of IL-13, INF-gamma, and CXCL-8 production in the lung microenvironment." (PMID 27738390, 2016). "STAT6 activation is an important downstream mediator of IL4/IL13 responses in these cells, supporting its role in driving alternative (M2) macrophage activation in sarcoidosis." (PMID 40521183, 2025). "We identified nine biomarkers (IL-1β, IL-6, IL-8, IL-13, VEGF, angiogenin, C4a, RANTES, and MCP-1) that significantly differ in the BAL of patients with HP and sarcoidosis and showed that RANTES and IL-6 are associated with fibrotic outcome." (PMID 40725075, 2025). "Elevated mRNA expression levels of IL-13, a key Th2 cytokine, have been detected in the peripheral blood of sarcoidosis patients." (PMID 39598118, 2024). "Levels of Th17 (IL17-A, IL17-F) and Th2 (IL-4, IL-13) cytokines tended to be less abundant in sarcoidosis patients relative to controls." (PMID 35668129, 2022). "Many cytokines implicated in sarcoidosis including IFN-γ and IL-2 (Type 1), IL-23 (Type 3), and IL-4 and IL-13 (Type 2) signal via the JAK – signal transducer and activator of transcription (STAT) pathway." (PMID 35668129, 2022). "The BAL exosomes from sarcoidosis patients induced higher levels of IFNγ and interleukin-13 production by PBMCs and CXCL-8 production by epithelial cells in comparison to that induced by exosomes from healthy individuals." (PMID 27738390, 2016). "Interestingly, many of the listed cytokines implicated in sarcoidosis pathogenesis, including IFN-g and IL-2, IL-23, IL-4, and IL-13, act via the JAK-signal transducer and activator of transcription (STAT) pathway." (PMID 36289785, 2022). "However, despite similar local responses at the site of disease, the systemic response varies between individuals as evidenced by significantly higher serum IL-4 levels (and the possible elevation of IL-5 and IL-13) in sarcoidosis." (PMID 22815689, 2012). "Based on our results, 9 possible biomarkers were identified (IL-1β, IL-6, IL-8, IL-13, VEGF, angiogenin, C4a, RANTES, and MCP-1) out of 18 tested that significantly differ in the BALF of patients with HP and sarcoidosis." (PMID 40725075, 2025). "In a study on sarcoidosis, a relatively higher amount of IFN-g and IL-13 was produced by exosome-stimulated peripheral blood mononuclear cells." (PMID 31374972, 2019). "There is a report of exosomes from bronchoalveolar lavage fluid of patients with sarcoidosis inducing pro-inflammatory cytokine release (IFNG and IL-13) from PBMCs, but it is unclear as to what concentrations of exosomes were used." (PMID 22848702, 2012). "Sarcoidosis patients had decreased levels of IL-1β, IL-5, IL-8, IL-12p70, TNF-α, angiogenin, C3a, C4a, RANTES, and MCP-1 and increased levels of IL-2, IL-4, IL-6, IL-13, IFN-γ, and VEGF." (PMID 40725075, 2025). "Occasional, weak IL13 expression was observed in the sarcoidosis cases, but it was not significantly different from controls." (PMID 35668129, 2022).
systemic sclerosis (17 papers, 2015 to 2025). A chronic disorder, possibly autoimmune, marked by excessive production of collagen which results in hardening and thickening of body tissues. "This allele, which is associated with lowest infection levels, has also been associated with allergic inflammation, an increased rate of IL13 transcription, and systemic sclerosis in individuals of European descent." (PMID 26540410, 2015). "Mutations in IL13Rα2, a decoy receptor that serves as an off-signal for IL13, are associated with systemic sclerosis." (PMID 26540410, 2015). "A fourth polymorphism, located in the 3’UTR of IL13, rs2243204, has been associated with systemic sclerosis in individuals of European ancestry; here too, the risk allele T occurs at higher frequency in African and African-American populations." (PMID 26540410, 2015). "In addition to polymorphisms in IL13, a polymorphism in IL13Rα2 associated with systemic sclerosis in individuals of European ancestry occurs with higher frequency in individuals of African ancestry." (PMID 26540410, 2015). "GATA3 has been reported highly expressed in peripheral CD8+ T cell from patients with systemic sclerosis, and functionally related to IL13 induction." (PMID 35095917, 2021). "Transforming growth factor (TGF)-β and interleukin (IL)-13 play a crucial role in the pathogenesis of systemic sclerosis (SSc), partly through activation of collagen production that leads to fibrosis." (PMID 26227022, 2015). "Indeed, the targeting of IL-4 and IL-13 has been tested in various fibrotic diseases, including systemic sclerosis." (PMID 37630981, 2023). "Our results show that two interleukins, IL-13 and IL-33, closely related to one another, are increased in a specific subset of systemic sclerosis patients with interstitial lung disease, a relevant complication conferring a high risk for mortality and morbidity." (PMID 35252259, 2022). "PF4 functions in integrin-dependent mechanism controlling angiogenesis, promotes the expression of pro-fibrotic cytokines such as IL-4 and IL-13, enhances the proliferation of regulatory T cells, and plays a role in multiple diseases including systemic sclerosis and antiphospholipid syndrome." (PMID 36091001, 2022). "In CTD-ILD, the autoimmune milieu often contains abundant Th2 cytokines; for example, patients with systemic sclerosis-ILD have elevated serum levels of IL-4 and IL-13, which favor M2 polarization." (PMID 41465549, 2025). "In patients with systemic sclerosis, TGF-β has even been shown to increase IL-13 synthesis in T lymphocytes, further highlighting its broad impact on immune regulation and fibrosis processes." (PMID 41465549, 2025). "However, a recent study found that IL-13 producing CD8+ T cells are involved in modulating dermal fibrosis in systemic sclerosisi (SSc) patients." (PMID 26176698, 2015). "While Romilkimab, which blocks IL-4 and IL-13, has been shown to effectively reduce dermal thickening in systemic sclerosis, it has not been shown to significantly improve lung function, underscoring the challenge of reversing fibrosis once established." (PMID 41465549, 2025). "When searching for “systemic sclerosis” and cytokines in the PubMed database, TGF-β had the highest number of hits, followed by IL-6, IL-4, tumor necrosis factor (TNF)-α, platelet-derived growth factor, IL-10, IL-13, IL-1, IL-2, and IL-17 indicating cytokines are related to the pathogenesis of SSc." (PMID 34064515, 2021).